BIN1 (bridging integrator 1)
Diseases named in the same sentence as BIN1 in open-access papers (continued):
Sharing a sentence is not in itself a finding about the gene and the disease.
Alzheimer disease (continued). "Likewise, neuronal BIN1 isoform with an intact clathrin-binding domain encoded by exons 13–16 is critical for neurotransmitter reuptake at the synapse, and abnormal BIN1 genotypes have been linked to Alzheimer’s disease." (PMID 28806752, 2017). "This timely perspective underscores the potential of modulating BIN1 activity to enhance cellular clearance mechanisms and offers hope for more effective interventions for Alzheimer's disease." (PMID 40808414, 2025). "In this review, we provide an accessible overview of how disruptions in autophagy and endolysosomal trafficking contribute to the neurodegeneration process in Alzheimer's disease, positioning BIN1 as a central mediator within this complex network." (PMID 40808414, 2025). "Altered BIN1 expression has been observed in Alzheimer’s disease brains, with a decrease in neuronal (long) isoforms and an increase in glial (short) isoforms, suggesting cell-type-specific dysregulation." (PMID 41465142, 2025). "It is considered the third most prominent genetic risk factor for late-onset Alzheimer’s disease, just after apolipoprotein E (APOE) and bridging integrator 1 (BIN1)." (PMID 37240249, 2023). "Bin1, for example, was identified as an Alzheimer’s disease locus through GWAS studies, and localizes to the axon initial segment and nodes of Ranvier acting downstream of c-myc, an injury-response transcription factor in RGCs." (PMID 35259089, 2022). "Genome-wide association studies have identified BIN1 (Bridging integrator 1) and RIN3 (Ras and Rab interactor 3) as genetic risk factors for late-onset Alzheimer’s disease (LOAD)." (PMID 35241726, 2022). "Compared with these studies, we used a stricter P value cutoff with multiple testing correction and were able to replicate associations between BIN1, CD33 and Alzheimer’s disease and those between GPNMB and Parkinson’s disease." (PMID 37118290, 2022). "These traits can be categorized in three groups: traits related to brain ventricular volumes in particular the lateral-ventricle (GMNC and C16orf95), Alzheimer’s disease diagnosis (BIN1 and CR1), and measures of blood cell/lymphocyte counts (CR1)." (PMID 36066633, 2022). "Dysregulation of total BIN1 levels and splicing of these exons in the brain is correlated with Alzheimer's disease." (PMID 35544276, 2022). "For instance, in Alzheimer’s disease, the BIN1-vesicles of microglial origin contain tau protein and have paracrine seeding capacity on neurons, thus serving as a tau spreading mechanism during Alzheimer’s disease progression." (PMID 33669042, 2021). "BIN1 (an important protein in Alzheimer’s Disease, heart disease and cancer) is one of the few BAR proteins that bind to actin directly." (PMID 34104877, 2021). "Expression of BIN1 in a Drosophila model of Alzheimer’s disease was shown to modulate the toxicity of tau and the knockdown of BIN1 promotes tau propagation between neurons." (PMID 32500121, 2020). "We next confirmed that increasing tau phosphorylation, to mimic tau modifications in Alzheimer’s disease, affects the interaction of tau with BIN1 in cultured primary rat neurons." (PMID 32500121, 2020). "In support of this, the expression of the longer neuronal isoform of BIN1 is decreased and the shorter glial isoforms are increased in Alzheimer’s disease brain." (PMID 32500121, 2020). "We show that BIN1 is lost from the cytoplasmic fraction of Alzheimer’s disease cortex, and this is accompanied by the progressive mislocalization of phosphorylated tau to synapses." (PMID 32500121, 2020). "We find that BIN1 is lost in Alzheimer’s disease cytoplasm and that this correlates with tau accumulation in synapses and its loss from the cytoplasm." (PMID 32500121, 2020). "We show that, in Alzheimer’s disease, cortex BIN1 is lost from the cytoplasmic fraction and phosphorylated tau accumulates at synapses." (PMID 32500121, 2020).
Alzheimer disease (continued). "Genetic variants in PICALM, BIN1, CD2AP, and RIN3 are associated with increased risk of Alzheimer’s disease, all dementia, and suggested vascular dementia independent of the strong APOE ε4 allele." (PMID 30830563, 2019). "In this review we discuss our current knowledge of the risk genes APOE4, BIN1, CD2AP, PICALM, PLD3 and TREM2 and their impact on endolysosomal (dys)regulations in the light of late-onset Alzheimer’s disease pathology." (PMID 31159836, 2019). "We genotyped four variants in PICALM, BIN1, CD2AP, and RIN3 previously identified as top hits for Alzheimer’s disease, in two prospective studies of the general population totaling 74,754 individuals." (PMID 30830563, 2019). "Our study suggests that the contribution of genetic variation in BIN1 locus to AD risk might produce moderate effects that could lead to major outcomes with time, consistent with the small effect of common risk variants and with a late onset of Alzheimer’s disease." (PMID 31408457, 2019). "The repair response is also blocked by loss of calpain function, and is altered by loss-of-function mutations in the C. elegans orthologs of BIN1 and PICALM, well-established risk genes for late onset Alzheimer’s disease." (PMID 30497524, 2018). "For example, a region of excess French ancestry on chromosome 11 includes bridging integrator 1 (BIN1), and variation in this gene has repeatedly been associated with Alzheimer’s disease." (PMID 26966908, 2016). "Bridging integrator 1 (Bin1), also downregulated by PCP in this study, has been associated with Alzheimer's disease together with apoE." (PMID 23738220, 2013). "Given the growing evidence that TBI accelerates neurodegenerative processes and shares common molecular pathways with Alzheimer’s disease, assessing BIN1 expression provides important insight into how mild TBI affects neuronal membrane homeostasis and synaptic stability." (PMID 41516344, 2026). "Bridging integrator 1 (BIN1), triggering receptor expressed on myeloid cells 2 (TREM2), and zinc finger CW-type (ZCWPW1)/PWWP domain containing 1 (NYAP1) were identified in both all-cause dementia and Alzheimer's disease." (PMID 40949174, 2025). "Bridging integrator 1 (BIN1), traditionally recognized for its role in membrane remodeling and endocytosis, has recently emerged as a top genetic risk factor for Alzheimer's disease, linking cellular clearance mechanisms to the development of toxic amyloid-beta plaques and tau tangles." (PMID 40808414, 2025). "In addition, BIN1 has differentially expressed isoforms in the brains of Alzheimer’s disease patients." (PMID 40943121, 2025). "Study of miRNA involvement in Alzheimer’s disease pathogenesis is relevant, since the associations of protein-coding genes (APOE4, ABCA7, BIN1, CLU, CR1, PICALM, TREM2) with the disease revealed as a result of GWAS make it difficult to explain its complex pathogenesis." (PMID 38680184, 2024). "Amphiphysin II, also known as BIN1 (MYC box-dependent interacting protein-1 or bridging integrator-1) or SH3P9, is associated with cancer progression, several myopathies, heart failure, and late-onset Alzheimer's disease." (PMID 37859648, 2023). "Moreover, for the first time, our study shows a regulatory relationship between Bin1 and Ifitm3, two Alzheimer’s disease-related genes in microglia." (PMID 35526014, 2022). "Despite the importance of the endosomal pathway in β-amyloid production, the loss of neuronal BIN1 expression does not modulate β-amyloid pathology in a mouse model of Alzheimer’s disease (AD) amyloidosis." (PMID 35526014, 2022). "Our aim was to investigate the association of the genetic variant, rs744373 in the bridging integrator 1 gene (BIN1), the strongest genetic risk factor for Alzheimer’s disease after the APOE ε4 allele, with different cognitive domains among non-demented older men." (PMID 36280690, 2022).
Alzheimer disease (continued). "We hypothesize that disruptions to BIN1 proteins in Alzheimer’s disease affect normal tau functions in the extracellular space and promote phosphorylated tau-mediated synaptotoxicity." (PMID 32500121, 2020). "In Alzheimer’s disease brain, BIN1 may colocalize with neurofibrillary tangle-containing neurons and is associated with elevated tau phosphorylation." (PMID 32500121, 2020). "In total brain homogenates, we confirmed a trend towards reduction in BIN1 in severe relative to moderate stage Alzheimer’s disease and control tissues and significant increases in total and phosphorylated tau amounts with increasing disease severity, as previously reported." (PMID 32500121, 2020). "Taken together, our data suggest that tau phosphorylation in Alzheimer’s disease may disrupt cytoplasmic BIN1–tau interactions and allow unbound tau to mislocalize to synapses." (PMID 32500121, 2020). "However, we found marked and significant losses of cytoplasmic BIN1 in both moderate and severe Alzheimer’s disease tissues that correlated positively with reductions in cytoplasmic tau and inversely with increased synaptic tau." (PMID 32500121, 2020). "The longest neuronal isoform of BIN1 protein is reduced in end-stage Alzheimer’s disease brain." (PMID 32500121, 2020). "The purpose of this study was to determine whether alterations in BIN1 and tau in Alzheimer’s disease promote the damaging redistribution of tau to synapses, as a mechanism by which BIN1 polymorphisms may increase the risk of developing Alzheimer’s disease." (PMID 32500121, 2020). "BIN1 was first linked to AD in early genome-wide associated studies (GWAS) and remains second only to APOE in genome-wide significance in the recent meta-analysis of 94,437 individuals by the International Genomics of Alzheimer’s Disease Project." (PMID 32657270, 2020). "However, the role of the BIN1/Tau interaction, and its potential dysregulation in Alzheimer’s disease, is not yet fully understood." (PMID 30487734, 2018). "This method will enable researchers to carry out genetic polymorphism studies for genetic risk factors associated with late-onset Alzheimer’s disease (BIN1, CLU, ABCA7, CR1 and PICALM) without the use of expensive instrumentation and reagents." (PMID 23419238, 2013). "To date, promising research suggests that variants of TOMM40 or BIN1 may be relevant for assessing the risk of Alzheimer’s disease; however, they have not yet been recognized as standard diagnostic criteria for the condition." (PMID 41465142, 2025). "Studies have demonstrated that BIN1, a risk factor for late-onset Alzheimer’s disease (LOAD), co-localizes with Rab11, forms complexes with the AMPAR subunit GluA1, and contributes to maintaining normal spine morphology and AMPAR-mediated synaptic transmission in Alzheimer’s disease." (PMID 38203282, 2023). "The importance of neuroinflammation and microglia in Alzheimer’s disease has been highlighted by multiple GWAS, which have identified a number of single polymorphisms associated with risk for development of Alzheimer’s disease in several immune related genes, including TREM2, CD33, BIN1, and CR1." (PMID 31504240, 2019). "As Alzheimer’s disease (AD) is believed to be preceded by a long preclinical phase, it is important to unravel the association of BIN1 with cognitive function among non-demented individuals as this may provide evidence of the role BIN1 has in the development of AD." (PMID 36280690, 2022). "Bin1, a N-BAR protein, was established as a marker for Alzheimer’s disease due to its ability to shape membranes and its consistent presence in AD patients." (PMID 36212686, 2022). "Notably, BIN1 protein expression and its functional roles in microglia, a cell type most relevant to Alzheimer’s disease, have not been examined in depth." (PMID 35526014, 2022).
centronuclear myopathy (50 papers, 2008 to 2026). "In peripheral tissue, altered splicing or aberrant expression of BIN1 has been linked to cancer progression and centronuclear myopathy, and plasma BIN1 levels are associated with ventricular cardiomyopathy." (PMID 40835006, 2025). "The loss of T‐tubule components like bin1 and mtm1 results in the human disease known as centronuclear myopathy, which manifests with symptoms of myalgia, motor symptoms, respiratory symptoms, and exercise intolerance." (PMID 39840753, 2025). "Mutations in the BIN1 gene can lead to centronuclear myopathy, a condition that shares some histopathological features with myotonic dystrophy." (PMID 39248331, 2024). "Amphiphysin 2 (BIN1) is a membrane and actin remodeling protein mutated in congenital and adult centronuclear myopathies." (PMID 38724689, 2024). "BIN1-related centronuclear myopathy (BIN1-related CNM, OMIM#255200) is caused by mutations in BIN1 encoding amphiphysin 2, a ubiquitous protein implicated in membrane curvature and tubulation." (PMID 34768808, 2021). "The BIN1 gene is associated with autosomal recessive and dominant centronuclear myopathy (CNM), characterized by muscle weakness (myopathy), abnormal localization of nuclei, and growth retardation." (PMID 33829027, 2021). "Here, we focus on the cellular and physiological roles of amphiphysin 2 (BIN1), a membrane remodeling protein mutated in both congenital and adult centronuclear myopathies (CNM), that is ubiquitously expressed and has skeletal muscle-specific isoforms." (PMID 32994313, 2020). "BIN1 is mutated in different forms of centronuclear myopathies (CNM), characterized by muscle hypotrophy, muscle weakness, centralized nuclei and triad defects." (PMID 32994313, 2020). "Further studies will be necessary in the autosomal recessive CNM due to mutations in the BIN1 gene encoding Amphiphysin 232 in order to establish a potential common pathomechanism centered on satellite cell deficiency in the group of centronuclear myopathies." (PMID 30733559, 2019). "Disrupted membrane remodeling by BIN1 mutations is thus clearly connected with centronuclear myopathy, but the molecular mechanism underlying the effects of each point mutation in BIN1 on membrane interactions is poorly understood." (PMID 24755653, 2014). "We identified splice mutations affecting the muscle-specific BIN1 isoform in humans and dogs presenting a clinically and histopathologically comparable highly progressive centronuclear myopathy." (PMID 23754947, 2013). "In this study we identified and characterized the first mutation affecting the splicing of the muscle-specific BIN1 exon 11 in a consanguineous family with rapidly progressive and ultimately fatal centronuclear myopathy." (PMID 23754947, 2013). "The gene, BIN1, has recently been associated with two different muscle disorders: centronuclear myopathy (CNM, MIM #255200) and myotonic dystrophy (DM, MIM #160900 and #602668)." (PMID 23754947, 2013). "Human mutation of Bin1 is associated with centronuclear myopathy, a myopathy that also involves significant dysregulation of Ca2+ homoestasis in skeletal muscle." (PMID 21984944, 2011). "Mutations in BIN1 were identified in multiple individuals with autosomal recessive centronuclear myopathy." (PMID 21390209, 2011). "Mutations in BIN1 are associated to the autosomal recessive form of centronuclear myopathy, a disease characterized by muscle weakness, myofiber atrophy, and abnormal positioning of nuclei within muscle fibers." (PMID 21797990, 2011). "Human mutation of Bin1 is associated with centronuclear myopathy and SH3 domain of Bin1 is important for sarcomeric protein organization in skeletal muscle." (PMID 21984944, 2011). "We therefore focused on another protein of the membrane remodeling pathway that is similarly mutated in centronuclear myopathy, BIN1 (also called amphiphysin 2, NM_004305)." (PMID 20140253, 2010).
centronuclear myopathy (continued). "A similar technical approach was successfully utilized by Laporte and colleagues to examine T-tubule organization in centronuclear myopathy patients with BIN1 mutations." (PMID 19197364, 2009). "Mutations in both BIN1 and dynamin-2 result in centronuclear myopathy, a myopathy with similar pathologic features to myotubular myopathy." (PMID 19197364, 2009). "Mutations in the amphiphysin-2 (BIN1) gene on chromosome 2q14 have been recently identified in a small proportion of cases with the recessive form of centronuclear myopathy but further genetic heterogeneity is expected." (PMID 18817572, 2008). "Indeed, the perturbed BIN1-dynamin interaction is the cause of centronuclear myopathies, a heterogeneous group of inherited muscular disorders characterized by fiber atrophy and muscle weakness." (PMID 38724689, 2024). "Mutations in BIN1 cause centronuclear myopathy, which causes muscle weakness and atrophy." (PMID 37549140, 2023). "Mutations in the BIN1 gene are responsible for the CNM2 type of centronuclear myopathy (CNM)." (PMID 32164332, 2020). "Several other downregulated genes important for muscle development include BIN1/M-Amphiphysin2 (BIN1), which is frequently mutated in centronuclear myopathies, and muscle-restricted coiled-coil (MURC) playing the pivotal role in skeletal myogenic differentiation." (PMID 28545403, 2017). "This hypothesis is sustained by the findings that DNM2 is also mutated in an autosomal dominant form of centronuclear myopathy and that mutations of amphiphysin 2 (BIN1) have recently been identified in patients with an autosomal recessive form of CNM." (PMID 18429927, 2008). "Mutations in amphiphysin-2/BIN1, dynamin 2, and myotubularin are associated with centronuclear myopathy (CNM), a muscle disorder characterized by myofibers with atypical central nuclear positioning and abnormal triads." (PMID 25262827, 2014). "Homozygous BIN1 mutations in ubiquitously expressed exons are associated with autosomal recessive centronuclear myopathy (CNM), a mildly progressive muscle disorder typically showing abnormal nuclear centralization on biopsies." (PMID 23754947, 2013). "Some of the genes involved in centronuclear myopathies (BIN1 and RYR1) also exhibit alternative splicing defects in the skeletal muscles of individuals affected by DM1." (PMID 41303468, 2025). "Truncation of the protein-protein interaction SH3 domain of the membrane remodeling Bridging Integrator 1 (BIN1, Amphiphysin 2) protein leads to centronuclear myopathy." (PMID 38995680, 2024). "The connection of EHBP1L1 to BIN1 and DMN2 functions is particularly interesting due to BIN1 and DMN2 mutations being causative in forms of centronuclear myopathy." (PMID 36011338, 2022). "It has been shown that amphiphysin-2/BIN1, which is mutated in centronuclear myopathies, triggers peripheral nuclear positioning to the periphery of myofibers via N-WASP and actin, thus implicating the actin cytoskeleton in nuclear movement." (PMID 33557157, 2021). "A similar mechanism regulating vesicle fusion at the T-tubule would provide a common axis for the pathobiology of Bin1-, Dynamin2- or myotubularin-related centronuclear myopathies." (PMID 32709891, 2020). "Among these, mutations in myotubularin (MTM1), amphiphysin 2 (BIN1), and dynamin 2 (DNM2) lead to different forms of centronuclear myopathy (CNM)." (PMID 31680794, 2019). "Three mutations, K35N, D151N and R154Q, have been discovered so far in the BAR domain of BIN1 in patients with centronuclear myopathy (CNM), where impaired organization of T-tubules has been reported." (PMID 24755653, 2014). "Interestingly, several mutations have been identified in the BIN1 gene in patients with autosomal recessive centronuclear myopathy (CNM)." (PMID 24755653, 2014).